HIF1A (hypoxia inducible factor 1 subunit alpha)
Diseases named in the same sentence as HIF1A in open-access papers (continued):
Sharing a sentence is not in itself a finding about the gene and the disease.
colon carcinoma (continued). "Together, our results revealed that matrine inhibits colon cancer cell growth via suppression of HIF-1α expression and its downstream regulation of Warburg effect." (PMID 31849679, 2019). "Previous reports have demonstrated that Nrf2 increases HIF-1α–mediated angiogenesis in colon tumors and the migration of esophageal squamous cell carcinoma in the hypoxic tumor microenvironment." (PMID 31491980, 2019). "HIF1A expression increases in various types of cancer, such as breast, prostate, and colon cancer, and a high expression of HIF1A in a tumor indicates poor patient prognosis." (PMID 31744467, 2019). "We also revealed that the blocking of HIF-1α pathway using HIF-1α inhibitor 2-MEOE2 can significantly reduce PTBP3 induced colon cancer cell migration and invasion in cultured cell lines, as well as tumor growth in animal xenografts model." (PMID 31291975, 2019). "In the case of human colon cancer, HIF-1α staining was strong whilst HIF-2α staining was weak in late stage tumors, whereas the opposite has been documented in early stage tumors." (PMID 30761299, 2019). "Next we examined the effect of the knockdown of HIF-1α or HIF-2α on autophagy levels in colon cancer cells." (PMID 31151160, 2019). "In this article, we found that matrine inhibited the transcription of HIF-1α, thereby reversing the Warburg effect (inhibiting glucose uptake and lactate production) and suppressing cell growth in human colon cancer cells in vitro and in vivo." (PMID 31849679, 2019). "In the present study, we demonstrated that vanillic acid significantly inhibited HIF-1α protein synthesis and transcriptional activity in hypoxic-induced human colon cancer HCT116 cells." (PMID 30678221, 2019). "In colonic cancer patients, a similar trend was observed where high HIF-1α, MDR1 and LAPTM4B expression was correlated with advanced tumor stage, metastasis as well as chemotherapy treatment in isolated studies." (PMID 30746305, 2019). "In colon cancer, high expression of HIF-1α, MDR1 and LAPTM4B was correlated to clinical features of patients." (PMID 30746305, 2019). "HIF-1α suppresses Bcl-2 expression in colon cancer cells by inducing miR-210 expression, resulting in autophagy activation and radioresistance." (PMID 31817259, 2019). "In the current study there was an association of HIF-1α, MDR1 and LAPTM4B expression with advanced tumor stage, metastasis and chemotherapy treated group in breast, ovarian, prostate and colon cancer patients." (PMID 30746305, 2019). "The most intriguing finding, according to our opinion, is the mitochondrial localization of HIF-1α, that to our knowledge, it has been reported only once in colon cancer cells." (PMID 29584711, 2018). "Melatonin suppresses angiogenesis by inhibiting ROS production to reduce HIF-1α stabilization in colon cancer cells." (PMID 29725496, 2018). "Wogonin reversed hypoxia-induced multidrug resistance of human colon cancer cells via suppression of HIF-1α and glycolysis, by inhibiting the PI3K/Akt signaling pathway." (PMID 29898734, 2018). "Even if colon carcinoma cell lines present a basal activation of HIF1α pathways, the experiments in hypoxic condition allowed to identify substantial differences between metastatic and non-metastatic cells, in response to low oxygen partial pressure." (PMID 28061476, 2017). "In order to i) validate the effects of miR-675-5p on HIF1α and ii) confirm the crosstalk between miR-675-5p, HIF1α and EMT genes in colon carcinoma cells, we silenced miR-675-5p in hypoxic condition when HIF1α pathway is well established." (PMID 28061476, 2017).
colon carcinoma (continued). "Hypoxia inducable factor 1α (Hif1α) is another stability target gene of Rbm38 in the breast- and colon carcinoma cell lines MCF7 and HCT116." (PMID 28850611, 2017). "We investigated the possible role of HIF1α as mediator of miR-675-5p effects in colon carcinoma cells." (PMID 28061476, 2017). "Our results show that miR-675-5p, over expressed in metastatic colon cancer cells, participates to tumour progression by regulating HIF1α induced EMT." (PMID 28061476, 2017). "We had previously demonstrated that MSCs pre-treated by inflammatory cytokines such as TNF-α and IFN-γ in the tumor microenvironment express higher levels of VEGF via the HIF-1α signal pathway and promote colon cancer growth by enhancing tumor angiogenesis." (PMID 29268703, 2017). "In this study, we demonstrated fatty acid metabolism-facilitated colon cancer progression, and found that OA modulated fatty acid metabolism through HIF1α, inducing the inactivation of the Wnt signaling pathway and cell growth inhibition of colon cancer." (PMID 28594405, 2017). "Surprisingly, overexpression of STK33 in hypoxic HCT-116 colon cancer significantly boosted HIF-1α promoter activity beyond the levels achieved by hypoxic cells transduced with empty vector (lane 5 vs. lane 3)." (PMID 29100402, 2017). "In the HT-29 colon cancer cells, hypoxia induced a 3-fold increase in HIF-1α protein and mRNA expression with protein levels increasing after only 24 hours hypoxia." (PMID 29137421, 2017). "The diversity of proteins which interact with NQO1 has grown significantly and recent work demonstrated stabilization of HIF-1α by NQO1 in RKO colon tumors in mice xenografts as a result of impaired proteasomal degradation." (PMID 28883796, 2017). "Here, we report that PIN1 directly interacts with hypoxia-inducible factor (HIF)-1α in human colon cancer (HCT116) cells." (PMID 26784107, 2016). "The key findings of this study are that ZFP91 overexpression was significantly associated with progression of human colon cancer and that ZFP91 promotes colon cancer progression through upregulating HIF-1α in cooperation with NF-κB/p65." (PMID 27144516, 2016). "In this regard, we found another crucial role of ZFP91 other than NIK activation in cancer: ZFP91 was able to dramatically upregulate the expression levels of HIF-1α in colon cancer cells." (PMID 27144516, 2016). "Flow cytometry, 5-ethynyl-2′-deoxyuridine (EdU) incorporation and tumor xenograft assay demonstrated that ZFP91 enhanced cell proliferation of colon cancer through upregulating HIF-1α in vitro and in vivo." (PMID 27144516, 2016). "Like VEGF, PDGF enhanced human colon cancer proliferation, and increased oxidative glycolytic activity, and activated HIF1α and c-Myc in vitro." (PMID 27626684, 2016). "Stimulation with PDGF also resulted in increased HIF1α expression in HT29 colon cancer cells, which was further intensified after stimulation with VEGF (p<0.05) after 48 hours." (PMID 27626684, 2016). "Taken together, these results provided clear evidence for BRU-mediated HIF-1α regulation and suggested its therapeutic potential in colon tumors." (PMID 27982118, 2016). "In particular, Nrf2 blockade suppressed colon tumor angiogenesis by inhibiting HIF-1α and migration and invasion of esophageal squamous cell carcinoma cells in a hypoxic microenvironment." (PMID 27286880, 2016). "It has been documented that melatonin suppressed HIF-1α transcriptional activity thus leading to a decrease in its target gene VEGF expression in HCT116 human colon cancer cell line under hypoxic exposure." (PMID 27812200, 2016). "In summary, we report that ZFP91 promotes colon cancer progression through upregulating HIF-1α via NF-κB/p65." (PMID 27144516, 2016). "In this study, we have used rAAV genome editing technology to generate a HCT116 human colon cancer HIF-1α–NanoLuc reporter cell line." (PMID 26882567, 2016).
colon carcinoma (continued). "Thereafter, investigator in the realm of colon cancer has identified Nrf2 as an important factor in activating HIF-1α." (PMID 26922479, 2016). "The opposite result was reported for colon carcinoma cells in which HIF-1α inhibited Wnt/β-catenin activity." (PMID 26210994, 2015). "Inhibition of endogenous iNOS-derived NO production was able to reduce HIF1α stabilization and protein levels in colon carcinoma cells." (PMID 25849745, 2015). "Colon cancer cells with oncogenic KRAS mutation and expressing both HIF-1α and HIF-2α were shown to maximize ATP production and minimize ROS generation, probably through the induction of enzymes important for mitochondrial cardiolipin synthesis." (PMID 25590810, 2015). "We found that MC-38 mouse colon cancer cells contain functional hypoxic (HIF-1α) and inflammatory (p65/RelA) signaling pathways." (PMID 25978030, 2015). "In this study, we demonstrated that hypoxia-related up-regulation of PrPc protein inhibited TRAIL-mediated apoptosis and PrPc protein expression related to hypoxic conditions stabilized HIF-1α in colon cancer cells." (PMID 25742790, 2015). "Although LW6 is synthesized as an (aryloxyacetylamino)benzoic acid derivative and has the potential to inhibit the expression of HIF-1α in the HCT116 human colon cancer cell line, its mechanism of action has remained to be fully elucidated." (PMID 26017562, 2015). "Here we first revealed that CDCA and guggulsterone which has been therapeutically used to treat cholestatic liver diseases and colon cancer, directly reduced HIF-1α protein." (PMID 26098428, 2015). "To verify that the HIF-1α protein plays a protective role in hypoxic colon cancer cells via PrPc, we used PrPc siRNA to determine the effect of silencing PrPc in HCT116 cells." (PMID 25742790, 2015). "We determined the role of HIF-1α-mediated PrPc on the TRAIL-mediated apoptotic response observed in sh-mock or shPrPc transfected HCT116 human colon cancer cells using a xenograft model following intra-tumoral injection of TRAIL or PBS." (PMID 25742790, 2015). "In this study, we have shown that LPA increases MIF expression in colon cancer cells and its regulation is dependent on the transcription activation by HIF1α." (PMID 26352431, 2015). "In our previous study, metabolite of oltipraz (M2) was found to elevate miR-199a-5p and -20a/b levels, leading to the inhibition of HIF1A translation in colon cancer cells." (PMID 25714015, 2015). "The immunohistochemical staining was conducted for CA9 and HIF-1α to verify their protein expressions within the normal and colon tumor tissues." (PMID 26447758, 2015). "Advanced colon carcinoma patients with expression of both HIF-1α and P-gp were more resistant to chemotherapy than that with non expression." (PMID 24901645, 2014). "Particularly, in HCT-116 colon carcinoma cells, HIF-1α and HIF-2β regulate the cancer metabolism by overlapping with the KRAS oncogene." (PMID 24804733, 2014). "In order to establish the effect of the dipeptide L-carnosine on the expression of the HIF-1α transcription factor, human colon carcinoma cells (HCT-116) were treated with different concentrations of L-carnosine (from 0.5 to 100 mM)." (PMID 24804733, 2014). "It has been reported that HIF-1α protein is over-expressed in many types of human cancer, including lung, breast, prostate, stomach, and colon carcinomas." (PMID 24804733, 2014). "We investigated CXCR4 and CXCR7 mRNA and protein expression in human colon carcinomas and the modulation of their expression by hypoxia and HIF-1α in colon cancer cell lines." (PMID 24629239, 2014). "Our novel finding that 15-LOX-1 inhibited HIF-1α protein expression in colon cancer cell lines elucidates the mechanisms by which 15-LOX-1 expression in cancer inhibits angiogenesis and metastasis." (PMID 24634093, 2014).
colon carcinoma (continued). "In this study we demonstrated that mimicking hypoxia in vitro by using CoCl2, which stabilizes HIF-1α protein by inhibiting its degradation, is capable of generating PGCCs in colon cancer cell culture." (PMID 24932611, 2014). "It has also been shown that hypoxia, by means of HIF-1α activation, is capable of maintaining CSCs phenotype in colon cancer cells." (PMID 24932611, 2014). "We have previously shown that irinotecan inhibited HIF-1α protein accumulation in in vitro and in vivo models of colon cancer." (PMID 24629239, 2014). "This study aims to explore the molecular mechanisms of reversing colon cancer MDR by focusing on the target gene HIF-1α." (PMID 24901645, 2014). "HIF-1α inhibition reverses multidrug resistance in colon cancer cells via downregulation of MDR1/P-gp." (PMID 24901645, 2014). "In the present study, we aim to explore the potential molecular mechanisms and feasibility of reversing colon cancer MDR by focusing on the target gene HIF-1α." (PMID 24901645, 2014). "MMP2 expression was restrained after interfering HIF-1α expression in HCT116 colon cancer cells under hypoxia, by using siRNA." (PMID 25013467, 2014). "In this study, we evaluated the effect of L-carnosine treatment on HIF-1α activity in human colon cancer cells." (PMID 24804733, 2014). "To confirm that HIF-1α is induced under physiological conditions, we first cultured the colon cancer cell line, HCT116, at 5% O2, an oxygen tension found in vivo in tissues such as lung, brain, skin, liver and venous blood." (PMID 24835245, 2014). "Previous studies showed that irinotecan, a standard chemotherapeutic drug for metastatic colon cancer, has a cytostatic effect on xenografted colon tumors through the inhibition of HIF-1α expression." (PMID 24629239, 2014). "Although we initially identified a concordant relationship between FJX1 mRNA and HIF1-α mRNA expression in human colonic tumors, we were only able to attribute a post-translational role of FJX1 on HIF1-α regulation in vitro." (PMID 23922772, 2013). "The signaling behind S1P-evoked HIF-1α also resembles IGF-1-induced HIF-1α expression in colon cancer cells and angiotensin II-evoked HIF-1α expression in vascular smooth muscle cells." (PMID 23824493, 2013). "Although the expression of HIF-1α mRNA was detected in colon cancer cell lines, the addition of PSK suppressed HIF-1α mRNA expression in colon cancer cell lines." (PMID 23181101, 2012). "COX-2 was reported to be induced by hypoxia in colon cancer and was transcriptionally regulated by HIF-1α." (PMID 22992293, 2012). "VEGF is transcriptionally regulated by HIF-1α, resulting in overexpression in human colon cancer biopsies." (PMID 22992293, 2012). "The effects of PSK identified in the present study include the suppression of HIF-1α gene expression, the suppression of angiogenic growth factors and the enhancement of angiogenesis inhibitors in colon cancer cells." (PMID 23181101, 2012). "We also found that miR-22 controls hypoxia inducible factor 1α (HIF-1α) expression in the HCT116 colon cancer cell line." (PMID 21629773, 2011). "It has been shown that HIF-1α transcriptional machinery activated by hypoxia signaling pathway abrogates c-Myc activation of BRCA1 expression in colon cancer cells." (PMID 21668996, 2011). "We also found that high expression of HIF-1α, CXCR4, and VEGF is associated with increased metastatic potential in human colon cancer." (PMID 20953377, 2010). "We found a correlation of distant metastasis of colon cancer with combined high expression of all three HIF-1α, CXCR4, and VEGF markers." (PMID 20953377, 2010). "The 786-0 CCRCC cell line only expresses HIF-2α, whereas both the N1E-115 neuroblastoma cell line and the SW480 colon cancer line endogenously expressed HIF-1α, as well as HIF-2α." (PMID 20652061, 2010). "Conversely, in SW480 colon cancer cells, HIF-1α siRNA inhibits proliferation whereas HIF-2α siRNA increases anchorage independent growth." (PMID 20637078, 2010).
colon carcinoma (continued). "In order to quantify the message RNA of these marks in colon cancer, expression of HIF-1α, CXCR4, and VEGF at the mRNA levels was analyzed by real-time PCR in different samples." (PMID 20953377, 2010). "Immunohistochemical expression of HIF-1α was observed in the cytoplasm and in the nucleus of the tumor cells in colon cancer cases but with different staining intensities." (PMID 20953377, 2010). "Knockdown of HIF-1α through small interfering RNA in a colon cancer cell xenograft reduced tumour growth, but surprisingly did not inhibit tumour angiogenesis." (PMID 19623180, 2009). "We, therefore, investigated whether miR-22 modulates the HIF-1A pathway, as previously reported in colon cancer, by analyzing the expression of metabolic target genes." (PMID 40332478, 2025). "Furthermore, we used GEO dataset GSE10950 and tissue chips to assess P4HA2/VHL/HIF-1α/HILPDA signaling axis on colon cancer." (PMID 39920992, 2025). "MicroRNA-20a reduces HIF-1α and hence promotes autophagy in colon cancer cells." (PMID 40004215, 2025). "We further explored the effect of PKN2 on HIF‐1α in colon cancer cells under hypoxic conditions." (PMID 40515512, 2025). "We hypothesized that PP extract inhibits colon cancer cell migration, proliferation, and drug resistance under hypoxia by suppressing glycolysis and HIF-1α signaling." (PMID 40647184, 2025). "Moreover, PKN2 inhibited the expression and secretion of VEGFA and bFGF by colon cancer cells by inhibiting the binding of HIF‐1α to the VEGFA and bFGF promoter regions." (PMID 40515512, 2025). "Our results discovered that KynA reduces HIF-1α protein stability and promotes its degradation through the ubiquitin-proteasome pathway, thereby inhibiting the proliferation and liver metastasis of colon cancer." (PMID 39920992, 2025). "Furthermore, the ubiquitination of HIF‐1α was detected in colon cancer cells transfected with low and high doses of PKN2 plasmid." (PMID 40515512, 2025). "Additionally, HIF-1α activates miRNA-210, which potentiates autophagy and diminishes radiation sensitivity by repressing Bcl-2 expression in colon cancer cells." (PMID 40305214, 2025). "Meanwhile, Red ginseng inhibited the hypoxia-induced VEGF expression through the destabilization of the HIF-1α protein, suggesting that Red ginseng may block colon cancer cell invasion and migration by inhibiting these pathways." (PMID 41585262, 2025). "Notably, a robust association between HIF-1α mRNA and HITT has been substantiated in human colon cancer tissues." (PMID 40305214, 2025). "Additionally, PKN2 directly interacted with HIF‐1α at the protein level and induced phosphorylation, resulting in ubiquitination‐dependent degradation of HIF‐1α in colon cancer cells." (PMID 40515512, 2025). "Previous studies confirmed that regulating aerobic glycolysis is an important factor for Sishen Pill to treat colon cancer; whether it is related to HIF-1α remains to be determined." (PMID 38650627, 2024). "In addition, the B-RAF- and KRAS-driven colon cancer cells used in our analyses were “addicted to autophagy” because they overexpressed the hypoxia-inducible factors HIF-1α, HIF-2α, and HIF-3α, which promote autophagy." (PMID 38473963, 2024). "Further, HIF-1α activation can increase COX2 levels in colon cancer cells." (PMID 38612478, 2024). "Furthermore, PX-12 regulates metastasis of colon cancer cells by diminishing the expression of vascular endothelial growth factor and attenuating hypoxia-inducible factor 1 subunit alpha (HIF1A) levels." (PMID 39090114, 2024).